MDM2 (MDM2 proto-oncogene)
Diseases named in the same sentence as MDM2 in open-access papers (continued):
Sharing a sentence is not in itself a finding about the gene and the disease.
diabetes (18 papers, 2008 to 2025). "Vascular endothelial growth factor (VEGF) and mouse model minute 2 (MDM2)are upregulated in the retina due to diabetes, which increases the risk of DR." (PMID 39050338, 2024). "A thorough investigation of the role of MDM2 on DROSHA might bring new insight into the pathological process through which diabetes supports the loss of angiogenic capacity in these two tissues." (PMID 33801773, 2021). "The present study investigated whether diabetes promoted MDM2 expression in colon cells and the underlying mechanisms." (PMID 30271790, 2018). "Among smokers (p = 0.0070), alcohol drinkers (p = 0.0233), individuals with hypertension (p = 0.0041), diabetes (p = 0.0225), and those with a family history of cancer (p = 0.0020), the MDM2 rs2279744 GT and GG genotypes exhibited increased RCC risks." (PMID 39857959, 2025). "We then conducted stratified analyses based on epidemiological and clinical risk factors, including smoking, alcohol consumption, hypertension, diabetes, and family history of cancer, according to individuals’ MDM2 rs2279744 genotypes." (PMID 39857959, 2025). "In conclusion, our results showed that KLF5 directly transcribed MDM2 in vitro in a cell model and in vivo in diabetes mouse colon, which was responsible for AGEs-increased expression of MDM2." (PMID 30271790, 2018). "In conclusion, our results suggest that diabetes increases the level of AGE which enhances the expression of MDM2 via transcription factor KLF5 in colon cells." (PMID 30271790, 2018). "Our findings indicate that the MDM2 rs2279744 SNP is significantly associated with RCC susceptibility, particularly among individuals who smoke, consume alcohol, or have comorbidities such as hypertension, diabetes, or a family history of cancer." (PMID 39857959, 2025). "First, MDM2 rs2279744 genotypes were not only predictors of RCC susceptibility but also showed significant interactions with risk factors such as smoking, alcohol consumption, hypertension, diabetes, and a family history of cancer." (PMID 39857959, 2025). "We investigated whether KLF5 transcribed the MDM2 animal model of diabetes." (PMID 30271790, 2018). "The various biological processesregulated by PPARs are crucial in control of disorders such as diabetes,inflammation, and cardiovascular ailments, and ubiquitin ligases such as E6-APand MDM2 may present useful targets for pharmacological intervention andimproved PPAR-based therapeutics." (PMID 19107217, 2008). "While negative correlations have resulted between MDM2 and diabetes, smoking, metastasis and survival." (PMID 37081989, 2023). "Prominent genes were RHOA, AKT1, RAC1, MDM2, CDKN1A, and VEGFA, which play important roles in TGF-beta and mTOR signaling (KEGG database), signaling by Wnt and by NOTCH (Reactome database), and in complications in diabetes mellitus (DisGeNET database)." (PMID 35742976, 2022).
lipomatous tumors (18 papers, 2008 to 2025). "IHC may be particularly helpful in excluding histological mimics such as angiomyolipoma (HMB-45 positive), atypical lipomatous tumors (MDM2/CDK4 positivity), or other smooth muscle tumors with ambiguous features." (PMID 40625645, 2025). "Molecular testing for MDM2 amplification should be considered in recurrent lipomas, lipomatous tumors with equivocal cytologic atypia, large lipomatous tumors (>15 cm) without cytologic atypia, and lipomatous tumors lacking cytologic atypia in the retroperitoneum, pelvis, and abdomen." (PMID 36983010, 2023). "The most useful tests in reevaluating diagnosis were FISH (for assessing MDM2 amplification status to determine whether differentiated lipomatous tumours or pleomorphic tumours were ALT/WDL or DDL, resp)." (PMID 25165418, 2014). "In our MDT, for example, all subfascially located lipomatous lesions are biopsied, resulting in 114 mdm2-negative tumors and 51 atypical lipomatous tumors in our series, rendering an RMST for lipomatous lesions of 0.39 (39%)." (PMID 35406402, 2022). "The sample was negative for MDM2 gene amplification which has a 93.5% sensitivity for detecting atypical and malignant lipomatous tumors." (PMID 28088193, 2017). "One patient had 2 separate lipomatous neoplasms tested (1 positive for MDM2 amplification, the other negative)." (PMID 25810689, 2015). "Identifying MDM2 amplification by immunohistochemistry, FISH, quantitative PCR, or comparative genomic hybridization (CGH) may prove an adjunctive tool in the diagnosis of lipomatous neoplasms." (PMID 24279301, 2013).
chronic lymphocytic leukemia (17 papers, 2009 to 2025). "We have observed that Nutlin-3, an inhibitor targeting Mdm2, possesses the ability to reduce Tcl1 expression in primary B chronic lymphocytic leukemia cells." (PMID 38961268, 2024). "Previous studies demonstrated that a different inhibitor of MDM2, Nutlin-3, is indeed able to efficiently induce apoptosis in B-cell chronic lymphocytic leukemia (B-CLL)." (PMID 19958544, 2009). "In line with this, a search for factors that interfere with MDM2 inhibition identified MDMX as one of the main drivers of resistance, and MDMX overexpression correlates with poor response to nutlin-3a in chronic lymphocytic leukaemia (CLL) cells but not in AML cells." (PMID 34911439, 2021).
synovial sarcoma (17 papers, 2013 to 2025). "In contrast, synovial sarcomas (SS) frequently exhibit overexpression of CDK2, CDK4, and MDM2, loss of CDKN2A, and mutations in genes such as CDK 4/6." (PMID 38275873, 2024). "Of note, ancillary molecular studies testing of t(X;18)(p11.2;q11.2) for synovial sarcoma and MDM2 amplification can be invaluable in secure the diagnosis." (PMID 36059611, 2022). "Drug classes that have little effect on synovial sarcoma at the studied doses included modulators of the Wnt pathway and MDM2 inhibitors." (PMID 28056055, 2017). "A meta-analysis of 70 studies evaluating molecular analysis in the diagnosis and prediction of the prognosis of STS demonstrated that FISH for MDM2 amplification, RT-PCR for SYT-SSX fusion, and CTNNB1 mutation were useful for WDLPS/DDLPS, synovial sarcoma, and desmoid tumors, respectively." (PMID 39001377, 2024).
thyroid cancer (17 papers, 2013 to 2025). "We were therefore interested to study the levels of MDM2 also in the ML1 thyroid cancer cells as influenced by IU1." (PMID 37711852, 2023). "To confirm the data obtained on HeLa cells in human thyroid cancer cells, we transfected TPC1 with the MDM2 phosphorylation-deficient mutant (MDM2 S166A) or with the wild-type MDM2 (MDM2)." (PMID 36612117, 2022). "Recently, circTP53 was found to promote thyroid cancer cell proliferation by targeting miR-1233–3p/MDM2 axis." (PMID 35372340, 2022). "Thyroid carcinomas were classified as positive for MDM2 expression and for RSK phosphorylation when they exhibited diffuse nuclear/cytosolic staining in several cells (cut-off fixed at >5% of tumor cells compared to normal cell)." (PMID 36612117, 2022). "This confirmed our hypothesis that dual MEK and MDM2 inhibition will yield significant tumor growth inhibition in genomically matched colorectal and thyroid cancers." (PMID 35075200, 2022). "CircTP53 enhances tumor growth by regulating miR-1233-3p/MDM2 signaling in thyroid cancer." (PMID 34290668, 2021). "Notably, in addition to AML, adrenocortical carcinoma and thyroid carcinoma demonstrate decreased MTF2 levels and concomitant elevated MDM2 expression, suggesting that loss of MTF2 in adrenocortical carcinoma and thyroid carcinoma could impact disease progression and therapeutic response." (PMID 37895228, 2023). "In fact, it has been reported that adrenocortical carcinoma cell lines are responsive to small-molecule MDM2 inhibition in vitro, and in preclinical studies, combined MDM2 and MEK inhibition prolongs survival of thyroid carcinoma xenograft mice." (PMID 37895228, 2023). "Therefore, we investigated the cellular response to MDM2 and PPM1D inhibition in two different thyroid carcinoma cell lines, TPC1 and K1." (PMID 36456590, 2022). "In addition to well-known BRAF, RAS, and RET mutations, NGS technology facilitated detection of new somatic alterations in thyroid cancer such as MITF, MDM2, JAK3, FLI1, IDH1 etc., all in which the significance of thyroid cancer has not been delineated yet." (PMID 27871285, 2016).
mesothelioma (16 papers, 1996 to 2026). A usually malignant and aggressive neoplasm of the mesothelium which is often associated with exposure to asbestos. "We examined susceptibility of mesothelioma to MDM2 inhibitors, nutlin-3a and RG7112." (PMID 34230456, 2021). "Sarcomatoid/biphasic mesothelioma is characterized by higher levels of MDM2, HIF1alpha, necrosis and proliferation index, compared with the epithelioid subtype, which in turn is characterized by higher levels of inflammation." (PMID 26544728, 2015). "To date, no literature data are available about different levels of inflammation and necrosis across mesothelioma histotypes and overall correlation between molecular markers as MDM2/HIF1alpha and morphological changes." (PMID 26544728, 2015).